PLEKHS1 (pleckstrin homology domain containing S1)
Synonyms: hEL185; C10orf81; FLJ23537; bA211N11.2
Tractability: No criterion of Open Targets' tractability assessment is met for any kind of drug.
Gene: Protein-coding gene on chromosome 10 (113,751,262 to 113,783,429, forward strand). Ensembl gene ENSG00000148735.
Subcellular location (Human Protein Atlas): Centrosome; Vesicles
Gene Ontology:
Molecular function: protein binding
Genetic constraint (gnomAD): Loss-of-function variants: 34 observed, 31.86 expected, observed/expected ratio (o/e) 1.07, 90% interval 0.81 to 1.42. The upper end of that interval is the gene's LOEUF score, 1.42, which puts it in group 5 of 6, group 1 being the genes least tolerant of losing a copy. Missense variants: 286 observed, 323.09 expected, observed/expected ratio (o/e) 0.89, 90% interval 0.8 to 0.98. Synonymous variants: 112 observed, 113 expected, observed/expected ratio (o/e) 0.99, 90% interval 0.85 to 1.16.
Homologues: Orthologues: macaque PLEKHS1 (92% identical), chimpanzee PLEKHS1 (83% identical), dog PLEKHS1 (71% identical), rabbit PLEKHS1 (71% identical), pig PLEKHS1 (70% identical), mouse Plekhs1 (65% identical), rat Plekhs1 (64% identical), guinea pig PLEKHS1 (61% identical), zebrafish plekhs1.3 (19% identical), zebrafish plekhs1.2 (18% identical), Drosophila melanogaster dos (17% identical), zebrafish plekhs1.1 (16% identical), and 2 more. Paralogues in human: GAB2 (17% identical), GAB1 (16% identical), PHLDB1 (15% identical), GAB3 (15% identical), GAB4 (13% identical), PHLDB2 (13% identical), PHLDB3 (9% identical).
Diseases named in the same sentence as PLEKHS1 in open-access papers:
PLEKHS1 is named in the same sentence as 31 diseases in open-access papers, as found by Europe PMC text mining. Sharing a sentence is not in itself a finding about the gene and the disease. The quoted sentences say what the papers report.
bladder cancer (7 papers, 2020 to 2024). "In eastern China, the mutation frequencies of GPR126 intron 6, TERT, and PLEKHS1 promoters in UUT-UC patients were significantly lower than those in patients with bladder cancer." (PMID 34660295, 2021). "In addition to the hotspot mutation in the PLEKHS1 promoter region its mutations in encoding sequences are also identified in bladder cancer and other malignancies; and these mutations can be missense, truncating or inframe shifting." (PMID 32752127, 2020). "Besides, Over-expressed PLEKHS1 increases the risk of disease progression in bladder cancer." (PMID 37978443, 2023). "Some expression changes are detectable only in a subset of tumor entities, as demonstrated by the PLEKHS1 hotspot in bladder cancer." (PMID 35013316, 2022). "We previously identified, in our global cohort of 103 bladder cancer samples, high frequencies of two non-coding mutational hotspots: intron 6 of GPR126 in 45.6% and PLEKHS1 promoter in 29.1%." (PMID 33049910, 2020). "These proteins include LTN1 (ovarian cancer), GBE1, CACNA1E and ADCY10 (lung cancers), as well as PLEKHS1 and ADNP (bladder cancer)." (PMID 38951817, 2024). "Mutations at specific hotspots in non-coding regions of ADGRG6, PLEKHS1, WDR74, TBC1D12 and LEPROTL1 frequently occur in bladder cancer (BC)." (PMID 36658180, 2023). "It is thus evident from these observations that PLEKHS1 plays an oncogenic role in the pathogenesis of PTC and bladder cancer." (PMID 32752127, 2020).
thyroid cancer (7 papers, 2020 to 2026). "Limited data have linked PLEKHS1 promoter (PLEKHS1p) mutations with higher aggressiveness of thyroid cancer." (PMID 42080574, 2026). "Overexpression of Pleckstrin homology domain containing S1 (PLEKHS1) was associated with metastases, as well as shorter overall and disease-free survival in thyroid carcinoma." (PMID 33450964, 2021). "PLEKHS1 (pleckstrin homology domain containing S1) promoter mutations are a poor prognosis genetic marker for thyroid cancer." (PMID 32850325, 2020). "Pleckstrin homology domain containing S1 (PLEKHS1) is a poorly characterized factor, although its promoter mutations were identified in human malignancies including thyroid carcinoma (TC)." (PMID 32752127, 2020). "Nevertheless, the link of PLEKHS1 to human cancer has recently been established due to the identification of mutations in the PLEKHS1 promoter in several human malignancies including bladder, breast, lung, and thyroid cancer, as well as acute lymphocytic leukemia." (PMID 32752127, 2020). "PLEKHS1 demethylation induces local opening of chromosomes, which leads to the expression of PLEKHS1 in thyroid cancer." (PMID 34923978, 2021). "In accordance, we found that PLEKHS1 drove AKT hyperactivity, promoted metastasis and was associated with shorter survival in thyroid cancer." (PMID 34093793, 2021). "PLEKHS1 plays a role in aggressive thyroid carcinoma and can be a biomarker for predicting poor outcomes." (PMID 33450964, 2021). "The results presented herein reveal that PLEKHS1 is over-expressed in thyroid carcinomas including PTCs and ATCs, and its higher expression is associated with lethal ATCs as well as metastatic PTCs and shorter patient survival." (PMID 32752127, 2020). "Abnormal changes in PLEKHS1 demethylation may be a target of thyroid cancer; however, the mechanism of PLEKHS1 demethylation still needs further study." (PMID 34923978, 2021). "Indeed, the ectopic expression of PLEKHS1 in thyroid cancer cells increased the abundance of phosphorylated AKT." (PMID 32752127, 2020).
Obesity (4 papers, 2016 to 2021). Accumulation of substantial excess body fat. "PLEKHS1 has also been implicated as a potential mediator for the onset of T2DM in people with obesity." (PMID 34681810, 2021). "In their study, the gene expression in two transgenic rat models, one for obesity and one for T2DM, was evaluated to investigate potential genes involved in the onset of obesity-associated diabetes, with PLEKHS1 identified as one of two candidate genes." (PMID 34681810, 2021). "Non-coding mutations in PLEKHS1 are common in cancer and the increased expression of PLEKHS1 is associated with the mild elevation of blood glucose levels and insulin resistance in obesity." (PMID 34681810, 2021). "Furthermore, Plekhs1 was identified as a potential contributor to mild hyperglycemia relevant to obesity in a rat model." (PMID 30065754, 2018). "Further detailed research is needed to establish the relationship between PLEKHS1 and the IGF axis in BCa and determine how these phenomena overlap with T2DM and obesity." (PMID 34681810, 2021). "Further research is warranted to establish the relationship between PLEKHS1 and the IGF axis in BCa, as well as how such putative relationships overlap with T2DM and obesity and the pathogenesis and progression of BCa." (PMID 34681810, 2021). "The upstream region of the HABP2 gene is associated with migraines without aura, and the intergenic region between the PLEKHS1 and MIR4483 genes is associated with obesity − related traits." (PMID 27230431, 2016).
anaplastic thyroid carcinomas (2 papers, 2020 to 2023). "This study was designed to determine PLEKHS1 promoter hotspot mutations in papillary and anaplastic thyroid carcinomas (PTCs and ATCs) and to evaluate if PLEKHS1 expression influences clinical outcome." (PMID 32752127, 2020).
bladder tumors (2 papers, 2020 to 2023). "However, the PLEKHS1 promoter mutation occurs in almost the half of bladder tumors, but the presence of the mutation was not correlated with its mRNA expression, indicating a negligible effect of this genetic event on the PLEKHS1 transcription." (PMID 32752127, 2020).
gastric cancer (2 papers, 2022 to 2024). A primary or metastatic malignant neoplasm involving the stomach. "PLEKHS1 has been reported as a biomarker for the diagnosis and prognosis of gastric cancer." (PMID 38801557, 2024).
Insulin resistance (2 papers, 2020 to 2021). Increased resistance towards insulin, that is, diminished effectiveness of insulin in reducing blood glucose levels. "It was previously shown that PLEKHS1 participated in blood glucose regulation and insulin resistance in obese rats, while its exact roles in physiological and pathological settings are currently unclear." (PMID 32752127, 2020).
gastric adenocarcinoma (1 paper, 2022). "On the other hand, PLEKHS1 was significantly downregulated in gastric adenocarcinoma and showed an inverse correlation with tumor grade suggesting its protective role in GC." (PMID 35446856, 2022).
hepatocellular carcinoma (1 paper, 2023). A malignant tumor that arises from hepatocytes. "PLEKHS1 is one of the up-regulated DEGs in hepatocellular carcinoma and a poor prognostic indicator." (PMID 37978443, 2023).
liver fibrosis (1 paper, 2019). "Among the seven potential biomarkers FABP3, GALNT5, GPR84, ITGB6, MYEOV, PLEKHS1, and STRA6, we are particularly interested in GPR84 and STRA6 because they link to liver fibrosis that is a major risk factor in HCC and an independent risk factor of recurrence after hepatectomy." (PMID 31828095, 2019).
Lymph node metastasis (1 paper, 2020). "There was a significant association between PLEKHS1 over-expression and lymph node metastasis (p = 0.002), but not distant metastasis, likely due to the very few patients with distant metastasis (4/249) in the TCGA cohort." (PMID 32752127, 2020). "Lymph node metastasis occurred in 50/93 of PTC patients and the primary tumors from these patients expressed significantly higher levels of PLEKHS1 mRNA than those without lymph node metastasis (p = 0.026)." (PMID 32752127, 2020).
cancer (11 papers, 2017 to 2025). A tumor composed of atypical neoplastic, often pleomorphic cells that invade other tissues. "According to a genome-wide analysis, mutations in non-coding regions of PLEKHS1 were found in 14 types of cancers and are associated with poor prognosis." (PMID 35446856, 2022). "Approximately 40% of urothelial bladder tumors carry PLEKHS1 promoter mutations, exhibiting the highest frequency in all analyzed cancer types in TCGA datasets." (PMID 32752127, 2020). "Mutations in non-coding regions of PLEKHS1 were found in cancer patients according to a genome-wide analysis." (PMID 30065754, 2018). "More recently, mutations in the regulatory regions of other cancer-related genes have been identified, including recurrent mutations in the promoters of PLEKHS1, WDR74, SDHD, and FOXA1 that alter gene expression levels, TF binding and that are associated with poor prognosis." (PMID 29456552, 2018). "PLEKHS1 gene is the second gene after telomerase reverse transcriptase (TERT) gene showing frequent promoter somatic non‐coding mutations which could be involved in various cancers." (PMID 35446856, 2022). "Novel biomarkers such as pleckstrin homology domain-containing S1 (PLEKHS1) have been mentioned in the context of cancer progression, with particular interest shown in BCa." (PMID 38338835, 2024). "Although recurrently promoter or UTR mutations for PLEKHS1 and TBC1D12 have been reported in several cancers, the functional role of these genes in tumorigenesis still remains uncharacterized." (PMID 30755618, 2019). "Therefore, the expression of PLEKHS1 may be correlated with cancer prognosis." (PMID 37978443, 2023).
tumor (10 papers, 2017 to 2023). "Our ‘in-house’ RNAseq data demonstrate that increased PLEKHS1 expression is significantly associated with high-risk NMIBC (in both G3T1 tumours and CIS) and significant reductions in the expression of IGFBP-2, IGFBP-4, and IGF-1R." (PMID 34681810, 2021). "PLEKHS1 mutations can be detected in tumour DNA shed into the urine, making it a candidate biomarker for BCa." (PMID 34681810, 2021). "CIDEC was significantly down-regulated in tumor tissues, while EPS8L3, MUC13 and PLEKHS1 were significantly highly expressed in tumor tissues." (PMID 37978443, 2023). "Mutational status in TERT and PLEKHS1 promoters and GPR126 intron 6 was analyzed in tumor DNA derived from 164 patients with UTUC using Sanger sequencing." (PMID 34093793, 2021). "In multivariate analyses, PLEKHS1 over-expression, age (≥55 years old) and larger tumor size (>4 cm), but not gender and TERT promoter mutations, were independently associated with shorter patient OS." (PMID 32752127, 2020). "Interestingly, PLEKHS1 mRNA abundance in the mutant PLEKHS1 promoter-bearing PTC tumor was the fourth highest among all PTCs." (PMID 32752127, 2020). "In addition, EPS8L3, MLC13, and PLEKHS1 can enhance tumour invasion." (PMID 37978443, 2023). "UroAmplitude identified TERT, PLEKHS1, FOXQ1, KMT2C, and ERBB2 somatic events in urine collected prior to resection of an HG T1 multifocal tumor." (PMID 36233691, 2022). "In addition, RT-PCR results displayed that CIDEC was significantly reduced in tumor tissues, MUC13 was significantly increased in tumor tissues, EPS8L3 showed an up-regulated tendency, while PLEKHS1 was down-regulated in tumor tissues." (PMID 37978443, 2023). "CIDEC, EPS8L3, MLC13 and PLEKHS1 may be potential prognostic factors for STAD and can be used to assess the level of immune cell infiltration in tumour tissues." (PMID 37978443, 2023). "Additionally, a significant negative correlation between PLEKHS1 gene expression and tumor grades was found pointing to its probable protective role in GC." (PMID 35446856, 2022). "PLEKHS1 expression was significantly increased in G3T1 compared to G1Ta tumours (p = <0.01), whilst IGFBP2, IGFBP4, and IGF1R were significantly reduced in the more advanced tumour group (p = <0.010.03, <0.01, respectively), which were similar results to those observed in CIS." (PMID 34681810, 2021).
PLEKHS1 also shares sentences with these, for which no sentence is quoted: ovarian carcinoma (2 papers); acute lymphocytic leukemia (1); breast carcinoma (1); colorectal tumors (1); diabetes (1); Glucose intolerance (1); head and neck squamous cell carcinoma (1); Hyperglycemia (1); lung carcinoma (1); migraines (1); neurofibromatosis (1); Papillary Thyroid Carcinoma (1); prostate tumors (1); testicular germ cell tumor (1); thyroid nodule (1); thyroid tumor (1); upper tract urothelial carcinomas (1); urothelial bladder carcinoma (1).